LRIG1 (leucine rich repeats and immunoglobulin like domains 1)
Diseases named in the same sentence as LRIG1 in open-access papers (continued):
Sharing a sentence is not in itself a finding about the gene and the disease.
diabetes (1 paper, 2021). "Intriguingly, we identified diabetes-preventing LRIG1 alleles that were strongly associated with an increased BMI and hyperplastic adipose morphology, e.g. many small adipocytes given total body fat." (PMID 33469151, 2021). "However, because we also found that LRIG1 enhanced both BMP signaling and adipogenesis, it seems reasonable to speculate that the diabetes-preventing LRIG1 alleles may stimulate adipogenesis by enhancing BMP signaling." (PMID 33469151, 2021).
experimental autoimmune encephalomyelitis (1 paper, 2023). An autoimmune demyelinating disease of the central nervous system that is produced experimentally in animals by the injection of homogenized brain or spinal cord in Freund's adjuvant. "Agonistic monoclonal antibody (mAb) specific to Lrig1 or adoptive transfer of CD4+Lrig1+ T cells exhibits significant therapeutic efficacy in experimental autoimmune encephalomyelitis (EAE), IBD, and lupus animal models." (PMID 37666819, 2023). "A monoclonal anti-Lrig1 antibody significantly improves the symptoms of experimental autoimmune encephalomyelitis." (PMID 37666819, 2023).
low grade glioma (1 paper, 2023). A grade I or grade II glioma arising from the central nervous system. "A particular SNP in intron 2 of LRIG1, rs11706832, has been shown to increase the susceptibility for IDH1 mutated low-grade gliomas (LGG)." (PMID 37185361, 2023).
lung diseases (1 paper, 2021). "AHR and LRIG1 have been reported to be expressed ubiquitously in all tissues; and they are dominantly expressed in lung epithelium, suggesting that the expression pattern of AHR and LRIG1 plays an important role during the pathogenesis of lung diseases." (PMID 34576152, 2021).
lupus (1 paper, 2023). "The therapeutic activity of CD4+Lrig1+ T cells was comparable to that of methylprednisolone, a clinically used lupus medication." (PMID 37666819, 2023). "Similar therapeutic efficacy was observed when CD4+Lrig1+ T cells were adoptively transferred into lupus-prone (NZB/NZW) F1 mice." (PMID 37666819, 2023). "Consistent with the high therapeutic potential of CD4+Lrig1+ T cells in IBD and lupus animal models, the higher expression of the genes involved in functions of Treg cells or induced by Foxp3 was observed in CD4+Lrig1+ T cells than CD4+Lrig1− T cells." (PMID 37666819, 2023). "The therapeutic efficacy of CD4+Lrig1+ T cells was confirmed in chronic IBD and lupus genetic-animal model through the adoptive transfer, which is comparable to that of CD4+Foxp3+ T cells in the IBD model and CD4+CD25+ T cells or methylprednisolone in the lupus-prone model." (PMID 37666819, 2023).
metastatic melanoma (1 paper, 2021). A melanoma that has spread from its primary site to another anatomic site. "In a cohort of metastatic melanoma patients, we observe an association between LRIG1 and survival in the triple wild-type subtype and in tumors with high EGFR expression." (PMID 33947959, 2021). "Decreased LRIG1 expression was previously shown to associate with worse survival in metastatic melanoma." (PMID 33947959, 2021).
ocular-surface squamous neoplasia (1 paper, 2014). "In this study, we show the expression of LRIG1 as a novel potential marker for neoplastic transformation in ocular-surface squamous neoplasia (OSSN)." (PMID 24709893, 2014).
oligodendroglioma (1 paper, 2014). A well-differentiated (WHO grade II), diffusely infiltrating neuroglial tumor, typically located in the cerebral hemispheres. "In oligodendroglioma, LRIG2 expression is associated with poor survival, suggesting that LRIG2 might have different functions compared with LRIG1." (PMID 25353163, 2014).
osteoporosis (1 paper, 2024). A condition of reduced bone mass, with decreased cortical thickness and a decrease in the number and size of the trabeculae of cancellous bone (but normal chemical composition), resulting in increased fracture incidence. "This hypothesis not only provides a new perspective for understanding the pathogenesis of osteoporosis but also signals that future studies may reveal new strategies for intervention and treatment of osteoporosis by regulating the LRIG1/BMP axis." (PMID 39526243, 2024). "We hereby propose the hypothesis that BMP serves as a pivotal mediator in the potential genetic interplay between LRIG1 and osteoporosis." (PMID 39526243, 2024).
pancreatic cancer (1 paper, 2019). "A negative correlation was specifically found between LRIG1 or RALT and ITGα3 expression in pancreatic cancer samples." (PMID 30808960, 2019).
prostate tumors (1 paper, 2019). "Similar IHC analysis in three tissue microarrays (TMAs) containing 306 prostate tumor and 307 normal prostate tissue cores also revealed increased LRIG1 in PCa." (PMID 31792211, 2019). "When LRIG1 mRNA levels from each microarray dataset were extracted, normalized, and pooled for comparisons, the 662 prostate tumors showed much higher LRIG1 expression than the 280 normal samples." (PMID 31792211, 2019). "Among the 15 PCa datasets that had detectable LRIG1, LRIG1 mRNA was overexpressed in prostate tumors (T) compared to normal (N)/benign prostate tissues." (PMID 31792211, 2019). "The LRIG1 expression pattern in AD/AI prostate tumors is reminiscent of LRIG1 response to estrogen stimulation and ER inhibitors in breast cancer." (PMID 31792211, 2019). "Importantly, our results demonstrate that LRIG1 represents an androgen receptor (AR) regulated gene and exhibits tumor-suppressive functions in both xenograft and genetic prostate tumor models." (PMID 31792211, 2019). "Consistent inhibitory effects of LRIG1 on both AD and AI (castration-resistant) PCa xenografts as well as in two genetic prostate tumor models prompted us to ask whether LRIG1 might possess therapeutic potential." (PMID 31792211, 2019). "As LRIG1 is overexpressed in human PCa, we first asked whether transgenic (Tg) expression of LRIG1 might inhibit prostate tumor development in an autochthonous mouse model." (PMID 31792211, 2019). "Conceptually, this model may help explain persistent overexpression of LRIG1 in PCa and perhaps its continued efforts in neutralizing multiple oncogenic assaults resulting in the overall indolent nature of most prostate tumors." (PMID 31792211, 2019).
sebaceous adenoma (1 paper, 2015). A benign, well circumscribed neoplasm arising from the sebaceous glands. "In sebaceous adenoma of K14ΔNLef1 mice, Lrig1 was mainly confined to keratinocytes at the periphery of the tumour lobules (arrow)." (PMID 25608467, 2015).
serous ovarian cancer (1 paper, 2024). "Blood levels of LRIG1 have only recently been studied, and interestingly, the results from a high-grade serous ovarian cancer cohort showed that high levels were associated with poor prognosis." (PMID 38918827, 2024).
Splenomegaly (1 paper, 2023). Abnormal increased size of the spleen. "The adoptive transfer of CD4+Foxp3+ or CD4+Lrig1+ T cells markedly alleviated the IBD symptoms such as body weight loss, inflammation in the colon, splenomegaly, and histological score, while these IBD symptoms were observed in CD4+Lrig1− T cell recipients." (PMID 37666819, 2023).
triple-negative breast carcinoma (1 paper, 2022). An invasive breast carcinoma which is negative for expression of estrogen receptor (ER), progesterone receptor (PR), and human epidermal growth factor receptor 2 (HER2). "Our study contributes novel insight into mechanisms which repress LRIG1 in triple-negative breast cancer and demonstrates for the first time that targeted de-repression of LRIG1 in cancer cells is possible." (PMID 35440669, 2022).
vulvar cancer (1 paper, 2024). "The LRIG1 antibody used in this study has previously been used in an investigation of LRIG1 expression in vulvar cancer." (PMID 38918827, 2024).
tumor (94 papers, 2003 to 2026). "This is consistent with previous studies, in which LRIG1 is described as tumor-suppressor and is linked to a good prognosis for cancer patients." (PMID 41201961, 2025). "The less studied LRIG3, which is said to have similar functions to LRIG1, has also been described as a tumor suppressor and is linked to lower tumor grades and a better patient survival." (PMID 41201961, 2025). "Larger tumours, alongside the lower frequency of flat atypia in the Lrig1-null lungs, suggests loss of Lrig1 facilitates and/or accelerates pre-invasive disease progression into invasive LUSC." (PMID 34385275, 2022). "Across diverse cancer types, high expression of LRIG1 is associated with superior patient survival, in agreement with its tumour suppressor function." (PMID 35440669, 2022). "It was reported that the expression of LRIG1 was negatively correlated with tumor grade and associated with better survival in numerous tumors, which indicated that the functions of LRIG2 and LRIG1 were different in the progression of tumors." (PMID 36183058, 2022). "Decreased LRIG1 expression is consistently observed in cancer, across diverse tumour types, and is linked to poor patient prognosis." (PMID 35440669, 2022). "LRIG1 encodes a protein that negatively regulates epidermal growth factor receptor signaling, and its tumor-suppressive effects in cancer have been demonstrated." (PMID 34172056, 2021). "The high incidence of C to A transversions observed in the tumor exomes implies that the loss of one copy of Apc in Lrig1+/− colonic stem cells increased inflammation and led to the formation of DNA adducts due to the oxidation of guanine." (PMID 32059662, 2020). "Mutated tumor-suppressor genes, such as phosphatidylinositol-4,5-bisphosphate 3-kinase catalytic subunit alpha (Pi3kca), Neurofibromin 1 (Nf1), and Lrig1 were observed." (PMID 32059662, 2020). "The Lrig1-CreERT2/+;Apcfl/+ tumors displayed a hypermutated phenotype; each tumor exome contained a unique profile of ~ 100 mutated alleles predicted as ‘high impact’ based on amino acid sequences." (PMID 32059662, 2020). "In contrast to the results obtained previously, however, we found that LRIG1 loss was significantly correlated with tumor grade and nodal status." (PMID 32448168, 2020). "Subsequent functional studies in multiple human xenograft and two mouse genetic models establish that LRIG1, which is rarely mutated in PCa, acts as a functional tumor suppressor in PCa." (PMID 31792211, 2019). "The majority of genes in the PAC-5 signature (LAMA3, E2F7, SLC12A2, and LRIG1) have been reported to be associated with tumour progression in various types of cancer." (PMID 31703415, 2019). "The enhanced tumor regeneration in all 3 AR+ xenograft models upon LRIG1 knockdown was associated with increased cell proliferation and slightly reduced cell death." (PMID 31792211, 2019). "Reduced LRIG1 expression is linked to tumour aggressiveness, temozolomide resistance and radio-resistance." (PMID 29460007, 2018). "Our findings indicate that infection with H. pylori increases populations of murine gastric epithelial cells expressing both KLF5 and Lrig1, proteins implicated in tumor biology and stemness." (PMID 23372710, 2013). "Given the prominent role for NRG signaling in cancer, it has been often suggested that the loss of Lrig1 enhances tumor progression by inducing overactivation of the ErbB pathway." (PMID 20126551, 2010). "Indeed, high LRIG1 immunoreactivity in the primary tumor was significantly associated with LNM (adjusted OR 9.49, 95% CI: 1.80–50.05, P = 0.008)." (PMID 40702701, 2025). "Moreover, our team showed that tumour formation in K14-HPV8-CER mice is associated with an expansion of the Lrig1+ stem cell population." (PMID 35406439, 2022). "Thus, in the present study, the frequency of LRIG1 loss seemed to increase together with increasing aggressiveness of the tumor." (PMID 32448168, 2020).
tumor (continued). "LRIG1 inhibition of TRAMP tumors was associated with reduced tumor cell proliferation." (PMID 31792211, 2019). "LRIG1 is highly expressed on activated tumor-specific CD8+ T cells, and the VSIR-LRIG1 signaling axis inhibits T cell proliferation, survival, and effector function." (PMID 40940864, 2025). "LRIG1 plays a role in the regulation of growth factor signaling and is a tumor suppressor in many cancer types." (PMID 40702701, 2025). "While LRIG2 has been described as a tumor promoter, LRIG1 and LRIG3 have been identified as tumor suppressors in previous literature." (PMID 41201961, 2025). "Increased miR-92a expression diminishes the tumor suppressive function of LRIG1 in CSCs, potentially driving tumor initiation and progression." (PMID 40126350, 2025). "LRIG1, which fuses a leucine-rich repeat sequence and an immunoglobulin-like structural domain, exhibits significant tumor suppressor effects in cancer biology and is involved in fine regulatory processes in adult stem cells (SCs)." (PMID 39526243, 2024). "LRIG1 functions as a tumor suppressant and has proven to be a negative regulator of receptor tyrosine kinase signaling, as well as a promotor of bone morphogenic protein (BMP) signaling." (PMID 38918827, 2024). "EGFR, known for its significance in tumor proliferation and viability, is effectively controlled by LRIG1." (PMID 38790164, 2024). "Wd&TS mice have faster SCC onset, characterized by a more severe phenotype and an increased percentage of Lrig1 GL cells within the tumour mass with respect to TS mice." (PMID 37081165, 2023). "Previous studies suggest that Lrig1 shows the tumor suppressor activity via functioning as a negative regulator of the ErbB RTK family in the tumor microenvironment." (PMID 37666819, 2023). "In 2012, LRIG1 was classified as a tumour suppressor, with genetic ablation leading to increased expression of ErbB receptors and the development of highly penetrant duodenal adenomas." (PMID 35440669, 2022). "We detected significantly higher KI67 and significantly lower GFAP expression in the Lrig1 KO tumours than WT controls." (PMID 36420140, 2022). "More recently, LRIG1 was reported to function as a haploinsufficient tumour suppressor in a PDGF-induced experimental glioma model, in part through negative regulation of MET." (PMID 35440669, 2022). "Lrig1 has evolved as a tumour suppressor, which is feedback-induced by multiple oncogenic signals shown both in vitro and in vivo." (PMID 35406439, 2022). "Here, we sought to explore methylation at the LRIG1 CpG island, versus intronic regions, as hypermethylation of tumour suppressor genes in the CpG islands near the promoter is a well-documented feature of cancer." (PMID 35440669, 2022). "To determine the function of Lrig1 in GSCs, we first engineered genetically normal cultured adult mouse NSCs into tumour-initiating GSCs." (PMID 36420140, 2022). "In this study, we uncover further evidence of a regulatory relationship between the tumour suppressor and quiescence marker Lrig1 and the BMP signalling pathway." (PMID 36420140, 2022). "While not significant, higher levels of the stem cell markers Nestin, Vimentin and SSEA1 were also seen in the Lrig1 KO tumours." (PMID 36420140, 2022). "LRIG1 is a negative regulator of oncogenic receptor tyrosine kinases and a documented tumour suppressor." (PMID 35440669, 2022). "We found rare lineage tracing events from Lrig1-expressing cells to a squamous lesion in an AOM/DSS tumor." (PMID 35600339, 2022). "To explore the effect of Lrig1 overexpression on the tumour-initiating capacity of aggressive NPE-IE GSCs, we transplanted NPE-IE mLrig1 and parallel NPE-IE controls into the striatum of NSG mice." (PMID 36420140, 2022). "LRIG1 is a tumor suppressor that negatively regulates tyrosine kinase receptors (TKRs) signaling by inducing their degradation via ubiquitination and/or hindering the TKRs heterodimeric conformation." (PMID 34359928, 2021).
tumor (continued). "We performed a two‐stage chemical skin carcinogenesis experiment to investigate if skin‐specific LRIG1 overexpression in mice affects tumor initiation or progression." (PMID 33786987, 2021). "During the two‐stage chemical carcinogenesis, almost exclusively LRIG1‐TG mice developed melanocytic tumors starting 12 weeks after tumor initiation." (PMID 33786987, 2021). "Previous research has demonstrated feed-forward regulating mechanisms in tumour cells in which abnormal HER2 signal reduced LRIG1 protein expression, which led to upregulated HER2." (PMID 34257270, 2021). "At the molecular level, the encoded transmembrane protein LRIG1 acts as a negative regulator of growth factor signaling; the LRIG2 protein works as a tumor promotor; and the LRIG3 protein functions as a tumor suppressor." (PMID 33802837, 2021). "LRIG1, a transmembrane protein, has a tumor-suppressive effect, and its expression is down-regulated in a variety of cancers." (PMID 33462260, 2021). "Several studies have demonstrated that LRIG1 acts as a tumor suppressor by down-regulating ErbB and Met receptors, including EGFR." (PMID 32796636, 2020). "Our findings indicate that increased levels of miRNA92a diminish the tumor suppressive role of LRIG1 in the ALDEFLUOR-positive CSC population." (PMID 32316543, 2020). "Receptor tyrosine kinases can be inhibited by various tumor suppressors, most notably leucine-rich repeats and immunoglobulin-like domains 1 (LRIG1)." (PMID 31945087, 2020). "Leucine-rich repeats and immunoglobulin-like domains protein 1 (LRIG1) is a tumor suppressor that regulates various receptor tyrosine kinases, including ERBB2 and other epidermal growth factor receptor family members." (PMID 32448168, 2020). "Taken together, these analyses suggest that the observed correlations between LRIG1 status and MFS in the present cohort were probably mostly due to associations between LRIG1 status and tumor subtype and nodal status." (PMID 32448168, 2020). "The tumor-suppressive effects of LRIG1 were still observed in 4–7-month-old dTg prostates although the effects became attenuated." (PMID 31792211, 2019). "Their data showed that IL-17R is responsible for the mobilization of Lrig1-positive SCs in wound healing experiments and in tumours in response to wounding." (PMID 31060263, 2019). "Comparison of Hi-Myc and dTg prostates at different ages revealed that LRIG1 inhibited Hi-Myc mPIN and tumor development." (PMID 31792211, 2019). "Despite its overexpression in human PCa, LRIG1 expression correlates with better patient survival, suggesting a tumor-suppressive function." (PMID 31792211, 2019). "Specifically, LRIG1 knockdown in VCaP cells resulted in increased tumor incidence (P = 0.0019; χ2 test) and larger tumors (note that tumor weight comparison was not statistically significant due to the small number of regenerated tumors in the NS group)." (PMID 31792211, 2019). "Together, these cell and xenograft experiments reveal tumor-suppressive activities of LRIG1 in both AR−/lo and AR+ human PCa models." (PMID 31792211, 2019). "Previous studies largely supported our results by showing the tumor suppressor role of LRIG1 in multiple types of cancers." (PMID 31358815, 2019). "In a second model driven by Apc LOH (Apcfl/+;Lrig1-Cre), Oct1’s dominant activity is tumor suppressive, with more tumors of equal grade generated." (PMID 31059499, 2019). "LRIG1, a tumor suppressor and stem cell marker, induces proteasomal degradation of EGFR (and its other three ErbB family members) via polyubiquination." (PMID 31562318, 2019). "LRIG1 induction inhibited clonogenicity (P = 0.02, Student’s t-test) and tumor growth of PC3-Neu* cells." (PMID 31792211, 2019). "Functional studies reveal strong tumor-suppressive functions of LRIG1 in both AR+ and AR− xenograft models, and transgenic expression of LRIG1 inhibits tumor development in Hi-Myc and TRAMP models." (PMID 31792211, 2019).